TBK1 (TANK binding kinase 1)
Diseases named in the same sentence as TBK1 in open-access papers (continued):
Sharing a sentence is not in itself a finding about the gene and the disease.
infection (continued). "In our study, the data of western blot proved that infection of influenza virus could increase the expression of the innate immune system-related factors TLR3, TAK1, TBK1, IRF3, and IFN-β in Raw264.7 cells." (PMID 31975996, 2019). "Consistent with the mammalian TBK1, the expression of zebrafish TBK1 protein did not alter significantly after SVCV infection." (PMID 29441066, 2018). "In conclusion, we show that TBK1 spliced isoforms are important negative regulators which target TBK1 and IRF3 for disrupting the formation of the functional TBK1-IRF3 complex under physiological conditions and SVCV infection." (PMID 29441066, 2018). "To examine whether miR-199a can affect the TBK1-dependent pathway, we used western blotting to monitor the protein expression of TBK1, p-TBK1, IRF3, and p-IRF3 in J774a.1 cells a t 24 or 48 h post-infection." (PMID 30042930, 2018). "Since our results show that TBK1 is crucial for hMPV-mediated lfTSLP induction, whereas IRF3 is not, we finally sought to assess if TBK1 regulates the activation of NF-κB during hMPV infection." (PMID 29343779, 2018). "In addition, we observed that TBK1 silencing significantly reduced the production of IFN-β in J774a.1 and BMDM macrophages after 24 and 48 h post-infection with M. bovis." (PMID 30042930, 2018). "TBK1 and IRF3 were phosphorylated, along the time course of infection." (PMID 28102839, 2017). "Upon infection with DNA viruses, the majority of USP13-interacting STING is disassociated from USP13 and translocates to form puncta, thereby leading to increased ubiquitination of STING and boosted recruitment of TBK1." (PMID 28534493, 2017). "By complementing Tbk1−/− MEFs, we confirmed that lack of TBK1 increased the percentage of ubiquitin‐coated cytosolic S. Typhimurium at 4 h post‐infection." (PMID 27370208, 2016). "Unlike WT SNRNP200, the staining of the FLAG-SNRNP200 S1087L mutant shows neither relocalization of the protein nor colocalization with TBK1 into these cytoplasmic speckles upon infection, correlating with its lack of RNA binding." (PMID 27454487, 2016). "Although analysis of CVB3-infected cells indicate TBK1 is not activated or targeted for proteolysis during infection with this enterovirus the status of TBK-1 or IKK-ε in poliovirus-infected cells has not been examined." (PMID 26437794, 2015). "TRAF3, NEMO and TBK1 are cytosolic proteins, and their respective amounts remained unaffected by the infection in the presence or the absence of MG132." (PMID 22626058, 2012). "Moreover, Tbk1−/− MEF show marked defects in type I IFNs, Cxcl10, and RANTES gene expression after infection with either Sendai or Newcastle disease viruses or after engagement of the TLR3 and TLR4 by double-stranded RNA and LPS, respectively." (PMID 20090833, 2010). "Since both IRF3 and SVCV-P drive TBK1 phase separation, with IRF3 facilitating IFN production and SVCV-P inhibiting it by disrupting IRF3-TBK1 phase separation, we hypothesized that during SVCV infection, IRF3-TBK1 and SVCV-P-TBK1 droplets might interact and remodel into a new phase-separated state." (PMID 41363845, 2026). "In the same study, infection of moMΦ with Georgia 2007 strain down-regulated other receptors, such as interferon receptors (IFNAR1, IFNAR2, IFNGR) and interleukin receptors (IL4R, IL10RA, IL10RB, and IL17RA), as well as transcriptomic factors (e.g., FOS, JUN, and TBK1)." (PMID 40530033, 2025). "In addition, even infection of macrophages with the classical RIPK1/caspase-8–activating pathogen, Yersinia pseudotuberculosis, sensitized TBK1/IKKε-inhibited cells to enhance RIPK1/caspase-8 activation and death but also enhanced secondary caspase-1 activation." (PMID 40053580, 2025). "Again, VEEV-TC83-GFP infection was strikingly reduced by TRIM32 expression in the absence of TBK1." (PMID 38895352, 2024).
infection (continued). "In addition, Western blot results showed that compared with control cells, in 293T cell line knockout of HDAC8 significantly reduced the protein expression of RIG-I, MAVS, p-TBK1 and p-IRF3 during VSV-GFP infection, which are key regulators of RLRs signaling pathway and subsequent immune response." (PMID 39035358, 2024). "IEIs of TLR3-, IRF7-, UNC93B1-, TICAM1-, TBK1-, and interferon alpha and beta receptor subunit 1 (IFNAR1)-dependent type I interferon immunity have been described to underlie life-threatening COVID-19 pneumonia in patients with no prior severe infection." (PMID 37559153, 2023). "To further examine the interactions of PTK2B with STING, TBK1 and IRF3, we next performed endogenous Co-IP experiments with PTK2B antibody in RAW 264.7 cells with or without HSV1-GFP infection and found that PTK2B only pulled down STING and TBK1 regardless of the HSV1-GFP infection state." (PMID 37989995, 2023). "On the contrary, kinases IKKβ or TBK1 directly phosphorylate TRIM21 at residue S80 in the LxxIS motif of the RING domain to prevent B-Box inhibition, enhancing E2 binding, RING catalysis, NF-κB activation, and cytokine expression after DNA or RNA viruses’ infection." (PMID 36675197, 2023). "Moreover, we observed that wild-type TBK1, but not its mutants Y591F and Y591E, increased levels of phosphorylated IRF3 and Ifnb1 production induced by HSV1-GFP infection when PTK2B was co-expressed in TBK1-deficient MEF cells." (PMID 37989995, 2023). "When we inhibited the interferon-alpha/beta receptor (IFNAR), we found that silencing IFNAR does not significantly alter infection, confirming our hypothesis that TBK1 mainly exerts its anti-CVB role through the autophagy pathway." (PMID 36044516, 2022). "Similarly, the level of TBK1 phosphorylation at Ser172 was increased with infection time, but this phosphorylation was not affected at all when UL31 was overexpressed in cells." (PMID 35196784, 2022). "However, depletion of Gal8 (but not Gal3) efficiently prevented TBK1 phosphorylation upon infection, suggesting that Gal8 was necessary for efficient TBK1 activation upon Ad entry." (PMID 35857795, 2022). "Similarly, another TBK1 inhibitor, BX795, also significantly reduced parasite loads in infected cells, although this decrease was less pronounced when compared to amlexanox-induced infection suppression." (PMID 36405710, 2022). "Moreover, during infection, genes involved in the regulation of the NF-κB cascade (AZI2, TBK1 and NFKBIA) and NFKB1were transcriptionally unaltered in all the respiratory tract of alpacas may be preventing acute inflammation in response to MERS-CoV." (PMID 34029358, 2021). "To verify the effect of UL35 on TBK1 phosphorylation in primary HFF-1 cells, we infected HFF-1 stably expressing empty vector or UL35 with HCMV UL35stop and lysed cells 0, 2, 4, and 6 h post infection and analyzed activation of the PRR signaling pathway by immunoblotting." (PMID 32466380, 2020). "To ascertain the kinase responsible for phosphorylation on residue T308 of AKT during infection and its potential relationship with mTORC1 activation, we first infected wild-type and Tbk1-/- cells with WSN in the absence or presence of BX795, an inhibitor of PDPK1, TBK1 and IKKε." (PMID 28953980, 2017). "However, complementation of Tbk1−/− MEFs with wild‐type TBK1 did not significantly alter the percentage of GFP:LC3B‐positive S. Typhimurium at 1 h post‐infection, nor did complementation with TBK1ΔC or TBK1K38M." (PMID 27370208, 2016). "Intriguing enough, results of PLP2 overexpression system and MHV-A59 infection system proved that PLP2 formed an inactive complex with TBK1 and IRF3 in the cytoplasm and the presence of PLP2 stabilized the hypo-phosphorylated IRF3-TBK1 complex in a dose-dependent manner." (PMID 21364999, 2011).
infection (continued). "Infection with RNA viruses or transient transfection with dsRNA can directly and rapidly induce early ISGs, such as ISG15, through IRF3, after activation of the RIG-I/MAVS pathway and recruitment of TRAF3, an essential adapter which recruits the downstream IRF3 kinases TBK1/IKKε." (PMID 22022264, 2011). "In line with a previous report, our findings suggest that PEDV may exploit kinase-dependent pathways, such as MAPK/AP-1 and JNK/p38, via TRAF2, TRAF6, and TBK1 to enhance viral replication during the acute phase of infection in weaned piglets, whereas such modulation was absent in newborn piglets." (PMID 40589734, 2025). "Indeed, in the absence of TBK1, we observe (i) a disruption in autophagic flux, (ii) significant increases in intracellular viral burden and viral EV release, and (iii) elevated viral load in both in vitro and in vivo models of infection." (PMID 36044516, 2022). "Moreover, the protein levels of phosphorylated TBK1 (p-TBK1), p-IRF3, and p-p65 were analyzed to determine whether SAFA was indeed involved in the activation of type I IFN and inflammatory responses under SFTSV infection." (PMID 34788350, 2021). "Notably, much higher levels of phosphorylation of Tbk1 and Irf3 were stimulated by ISD and 2′3′-cGAMP than by the ECTV infection, indicating that ECTV might express some potent immunomodulators that are involved in the modulation of TBK1 and IRF3 phosphorylation." (PMID 29963044, 2018). "In addition, two weak protein bands were also detected in ZF4 cells with/without SVCV infection, which may represent other TBK1 isoforms." (PMID 29441066, 2018). "Importantly, to achieve productive infection, the inhibition of JAK-STAT pathway by Janus kinase (JAK) or TANK-binding kinase 1 (TBK1) inhibitors was required, although in several of the screened hepatocyte donors, even JAK-STAT inhibition could not rescue HBV infection." (PMID 26784218, 2016). "Infection with the SIRV strain rSC0163 resulted in increased protein expression of cGAS, p-STING, p-TBK1, and p-IRF3 compared with infection by the non-SIRV strain rSC0162." (PMID 40876118, 2025). "HSV-1-and L. monocytogenes-infection induced S-nitrosylation of endogenous STING in PMs, but not cGAS, IRF3 or TBK1." (PMID 38409248, 2024). "Using the luciferase reporter assay system, our previous study and the present study revealed that TBK1 isoforms, TBK1_tv1–TBK1_tv3, had the same function in inhibiting RLR-mediated type I IFN production with or without SVCV infection." (PMID 33101307, 2020). "Western Blot analysis revealed cleavage of TBK1, but not of MAVS or IRF3, during wt FMDV-A12 infection." (PMID 32667958, 2020). "In contrast, we found, enhanced productive infection of DCs exposed to HIV-C also increases IRF3 activation and phosphorylation of TBK1 only in WT-THP1-DCs and CD11b KO THP1-DCs, but not CD11c KO THP1-DCs." (PMID 32922405, 2020). "TBK1 cleavage was observed from 4 hpi onwards upon infection with wt FMDV, but not upon infection with leaderless FMDV." (PMID 32667958, 2020). "We further confirmed that the increase in cytosolic Ca2+ during infection is not affected by knockout of STING, TBK1, and TBC1D9, suggesting that TBK1 activation is not required for Ca2+ elevation." (PMID 32034138, 2020). "Unlike mammalian TBK1s, expression of zebrafish TBK1 isoforms remains unchanged both in mRNA and protein levels during SVCV infection." (PMID 29441066, 2018). "Second, zebrafish TBK1_tv1 and TBK1_tv2 bound to TBK1 and IRF3 in mammalian and fish overexpression systems with/without SVCV infection." (PMID 29441066, 2018). "Nevertheless, the previously validated let-7e targets Tnfpaip3, Map2k4, Tbk1, and Tnf were upregulated during L. amazonensis infection, whereas the decrease in Chuk/IKBKA and Il10 expression during infection was not reversed by let-7e inhibition." (PMID 30555476, 2018).
infection (continued). "In ZF4 cells with/without SVCV infection, endogenous expressions of TBK1 normal form (~80 kDa) and TBK1_tv1 isoform (~70 kDa) remain unchanged in response to SVCV infection." (PMID 29441066, 2018). "BX795, a TBK1 inhibitor, and RU.521, a cGAS inhibitor, did not inhibit the EV-D68-induced IFN-β production, demonstrating cGAS-STING-independent IFN-β production in response to EV-D68 infection." (PMID 39459875, 2024). "Likewise, a truncated version of TBK-1 that binds to RIG-I, but not the downstream interactor MAVS (also known as VISA, CARDIF, and IPS-1), is expressed as early as 6h after infection of Sendai virus, effectively disrupting the innate immune response." (PMID 35127560, 2021). "Interestingly, by day 7 of infection, multiple genes were elevated in young H1N1 infected lung, such as Atg5, Mapk8, Tbk1, Casp8, and Ripk1, that were not similarly expressed in response to H3N2." (PMID 34829979, 2021). "Infection with ERAV, but not EMCV, resulted in the cleavage of TBK1." (PMID 32667958, 2020). "However, infection with WT HSV-1, but not ΔUL46 HSV-1, inhibited the phosphorylation of TBK1 and IRF3 induced by ISD, which is critical for IFN-I production." (PMID 31113902, 2019). "However when antiviral factors induced in MDM by LPS were tested during infection in the presence of BX-795, they largely maintained activity and inhibited HIV-1 replication, indicating that TBK1 is not essential for their antiviral function." (PMID 21904615, 2011). "Accordingly, while our findings support a model in which ALTO helps restrain replication through TBK1 activation, they do not directly demonstrate regulation of viral latency, and definitive proof of ALTO’s role in latency will require more complex systems that capture long-term infection dynamics." (PMID 41277846, 2025). "Interferon regulatory factor 3 (IRF3), but not TANK-binding kinase 1 (TBK1) and IκB kinase epsilon (IKKε), is sequestered into viral inclusion bodies (IBs) upon Ebola virus (EBOV) transcription- and replication-competent virus-like particles (trVLPs) infection." (PMID 38285487, 2024). "Notably, infection with EMCV Lpro L143A, which displayed wt deISGylase/DUB activity but is strongly impaired in its ability to cleave/degrade RLR signaling proteins MAVS, TBK1 and NFκB p65, failed to suppress the induction of IFN-β mRNA." (PMID 32667958, 2020).
tumor (224 papers, 2009 to 2026). "TBK1 is involved in various aspects of tumorigenesis, including supporting tumor angiogenesis, mediating tumor-associated autophagy, regulating the cell cycle and mitosis, and inducing epithelial-mesenchymal transition (EMT)." (PMID 40822284, 2025). "Concurrent silencing or inhibition of both TBK1 and IKKε also reduces tumor sphere growth in MIA PaCa-2 cells, correlating with a loss of stemness pathways found with RNA-Seq." (PMID 40738190, 2025). "Compared to the control group, the expression of STING and TBK1 was higher, and the tumor volume in the LAMP2A-deficient group was smaller with longer survival times, which was consistent with the results from in vitro experiments." (PMID 40083918, 2025). "We observed that sensitized tumor cells fail to recruit sufficient levels of pro-survival checkpoint kinases TBK1 and IKKε to Complex I, resulting in the loss of inhibitory Ser25 phosphorylation and an increase in activating Ser166 phosphorylation on RIPK1." (PMID 41315176, 2025). "Previous publications have implicated roles for TBK1 and IKKε in several cancer types, including work on pancreatic cell lines and tumor models." (PMID 40738190, 2025). "Significantly, TBK1 and TBK1+IKKε KOs showed heighten sensitivity not only to T cells, but also NK cells, suggesting their involvement in a broader mechanism of tumor susceptibility to immune cell attack." (PMID 41315176, 2025). "The aberrant activation of TBK1 contributes to the proliferation and survival of various types of tumor cells, particularly in specific mutational or tumorous contexts." (PMID 39161768, 2024). "This study shows that innate immune signaling via cGAS-STING or RLR-MAVS regulates tumor-associated macrophage tissue residency through activation of the TBK1-Zyxin axis." (PMID 39304793, 2024). "Regulation of IFN-I expression is a significant mechanism underlying TBK1’s role in tumor development." (PMID 39161768, 2024). "One of the primary motivations fordeveloping TBK1 inhibitors is their potential as anticancer agents.TBK1 has been implicated in promoting tumor growth and progressionin certain types of cancer by enhancing cell survival, proliferation,and metastasis." (PMID 39289178, 2024). "Deletion of Tbk1 in tumor epithelial cells reduces the number of both PD-L1 expressing cells and MDSCs in the tumor microenvironment, the reduction being associated with a local increase in CD8+ T-cells." (PMID 35395857, 2022). "Such anti-tumor activity of TBK1 has recently been discovered in a mouse model of Apc-mutated intestinal tumors." (PMID 35395857, 2022). "High TBK1 expression in tumor tissues is associated with reduced tumor-infiltrating CD8+ T-cells and increased immunosuppressive markers; thus, upregulation of TBK1 serves as a negative prognostic indicator for HCC patients." (PMID 35395857, 2022). "Expression of oncogenic alleles of KRAS induced cell death in TBK1-deficient murine embryonic fibroblasts, suggesting that RalB-Sec5-TBK1 controls a cell-autonomous host defense signaling pathway that inhibits tumor cell apoptosis." (PMID 30791439, 2019). "We determined the expression of IKKε and TBK1, and co-expression of IKKε and TBK1 was associated with differentiated intestinal histology and earlier tumor stage." (PMID 27145266, 2017). "Although adapter proteins are not druggable, interference with adapter-associated enzymes such as TBK1/IKKɛ can be useful to restrict aberrant bypassing of signaling pathways in tumor cells." (PMID 24217713, 2013). "Consequently, the direct loss of TBK1 and IKKε in tumor cells leads to heightened sensitivity to both CD8 T cell and natural killer (NK) cell killing." (PMID 41315176, 2025). "Importantly, in inflammation-associated cancers, we discuss the effect of TBK1 on tumors from the perspective of its regulation of tumor inflammation, which also provides new ideas for the treatment of such diseases." (PMID 40076567, 2025).